CAV1 (caveolin 1)
Diseases named in the same sentence as CAV1 in open-access papers (continued):
Sharing a sentence is not in itself a finding about the gene and the disease.
tumor (continued). "The expression of POSTN, TNC, CAV1 and FSCN1 was localized predominantly in the cytoplasm of the tumour cells." (PMID 33739025, 2021). "In our study, the expression of POSTN, TNC, CAV1 and FSCN1 found to be localized predominantly in the cytoplasm of the tumour cells." (PMID 33739025, 2021). "PI3K/AKT activation and β-Catenin-TCF/LEF-dependent activity downstream from Caveolin-1 also correlates to increased VEGF expression and thus greater angiogenic potential of tumor." (PMID 33718218, 2021). "Indeed, CAV1 expression in p16-negative tumors was predominately localized in less differentiated tumor cells with increasing epithelial CAV1 expression levels according to increasing tumor grades and thus decreasing differentiation patterns of the tumor cells." (PMID 33868995, 2021). "About CAV1’s role in OSCC, overexpression in the cytoplasm of OSCC and its upregulation was in sync with tumour progression." (PMID 33739025, 2021). "Own studies further confirmed that CAV1-dependent AKT signaling, among others, is an important factor for modulating tumor as well as stromal cells proliferation and survival upon cancer therapy." (PMID 33868995, 2021). "Overall, the interaction between DLC1-START, Caveolin-1, PLCD1, and phosphatidyserine (PS) contributes to DLC1 tumor suppressor function(s) in a RhoGAP-independent manner." (PMID 34727930, 2021). "In fact, the epithelial portion of the tumor consistently expresses CK14 and CK19, while other markers, such as Vimentin, Amelogenin, Glut-1, MOC-31, and Caveolin-1." (PMID 32040459, 2020). "Understanding the CAV1-dependent crosstalk between tumor cells and the host-derived tumor microvasculature and its impact on radiosensitivity may allow to define a rational strategy for overcoming tumor radiation resistance improving clinical outcomes by targeting CAV1." (PMID 32273493, 2020). "Cav-1 over-expression can increase GLC-82 cell proliferation, and an obvious tumor growth was also observed in mice models transplanted with such cells." (PMID 31991790, 2020). "The Src inhibitor SU11333 markedly inhibits tumor growth, by inhibiting Src-mediated vascular permeability and Src-mediated activation of STAT3, CAV-1 and FAK." (PMID 32456226, 2020). "Nab-PTX is associated with increased uptake by utilising the endogenous albumin pathways of gp60- and Cav-1-mediated endovascular transcytosis and binding between albumin and SPARC, which enables the drug to more thoroughly permeate the tumour." (PMID 32532230, 2020). "Treatment with eliglustat in RM-9 tumor bearing mice also resulted in statistically significant increases (two-sided Wilcoxon rank sum test p: 0.004) in plasma ceramides, suggesting that the elevation in plasma Cav-1 and sphingolipids may be a consequence of cell death." (PMID 32855410, 2020). "CAV1 (OMIM # 601,047) is expressed in a variety of tumor cells and exhibits carcinogenic and tumor suppressive functions dependent on the specific type of cancer and stage (Gupta, Toufaily, & Annabi, 2014)." (PMID 32243098, 2020). "By contrast, the overexpression of both WNT6 and Cav1 decreases cell death, indicating that Cav1 activates WNT6 to prevent tumor cell apoptosis, and induces chemoresistance through the β-catenin-dependent WNT pathway." (PMID 33425886, 2020). "Astragaloside IV (Astragalus membranaceus extract) suppresses tumor progression through inhibiting Akt/GSK-3β/β-catenin signaling axis and enhances chemosensitivity via targeting caveolin-1 (CAV-1), which led to oxidative stress." (PMID 32499699, 2020). "Cav-1 functions as a tumor suppressor in SCLC and is inversely required for tumor cell survival and growth in NSCLC." (PMID 31297035, 2019). "Cav-1 and membrane type 1 matrix metalloproteinase (MT1-MMP) co-localize and co-express in invadopodia, resulting in ECM degradation and tumor invasion and migration." (PMID 31759347, 2019).
tumor (continued). "Western blotting analyses on tumor protein extracts from ATV and vehicle groups indicated that ATV inhibited Cav1 and GLUT3 expression while pro-apoptotic Bax was up regulated, compared to vehicle." (PMID 31534543, 2019). "In conclusion, we do not know for sure in which tumors and to what extent the expression of caveolin-1 and the subsequent remodeling of the ECM in the tumor stroma has an influence on metastasis." (PMID 31845646, 2019). "The expression of relevant molecular biomarkers of both tumor types, analyzed in all PDXs, was also faithfully mirrored by PDX, in particular SATB2 and PGP in OS PDX, CD99 and caveolin 1 in EW PDX." (PMID 31434953, 2019). "In previous work, we identified an inverse relationship between the expression levels of CAV1 and the presence of HER2 protein at the tumor cell membrane." (PMID 31171598, 2019). "Caveolin-1 (CAV-1), which is an oncoprotein and a tumor suppressor, was demonstrated to be downregulated in OS cells, and overexpression of CAV-1 in human OS cells suppressed taxol resistance by attenuating PI3K-Akt-JNK-dependent autophagy." (PMID 30153287, 2018). "When inhibition of CAV1 or IGF1R was applied, it corrupted the complex allowing apoptotic molecules to resume mitigating tumor development." (PMID 30042829, 2018). "There are a further eight tumor-suppressor genes (DLEU2, CDKN2C, SPRY4, UBE2QL1, LIN9, TFPI2, LRIG3, DUSP1) and six genes serve as both oncogenes and tumor-suppressor genes (FOXO1, CAV1, KLF6, CDK6, PLK1, CTGF)." (PMID 30563222, 2018). "Altogether, these data indicate that CAV1 depletion stabilizes HER2 at the cell membrane and improves the tumor avidity for trastuzumab on HER2-positive cancer cells." (PMID 30510281, 2018). "For example, MES GBMs (red arrows) were enriched for CAV1, CD44, CD63, RAB27A, SDCBP and SMPDL3A, while PN (blue arrows) tumours contained higher levels of transcripts for ANXA6, CD81, hnRNPA2B1, YBX1 (RNA binding proteins) and RAB35." (PMID 30034643, 2018). "In agreement with our previous analyses of primary tumours, immunocytochemistry of a 3D-cell culture model upon formalin-fixation and paraffin-embedding (FFPE) recapitulated the inverse correlation in CAV1 and E-cadherin protein expression." (PMID 29402961, 2018). "In this study, we showed that the expression of CAV1 and CAV2 is deregulated in stromal cells of the primary tumor as well as in the stroma of lymph nodes." (PMID 29850392, 2018). "Similar results were obtained in tumors with co-implanted Cav1-silenced HS5 cells and thus an increased reactive tumor stroma and increased Akt levels." (PMID 28112237, 2017). "As compared to Cav1-expressing PC3(+)-tumors, PC3(−)-tumors contain a more collagenous tumor stroma as revealed by the increased blue-green stromal compartment after a Masson’s Goldner Trichrome staining." (PMID 28112237, 2017). "Therefore it has to be elucidated whether Cav1-dependent resistance-promoting signals from endothelial cells (EC) can be separated from Cav1-dependent stromal signals that restrict tumor growth and may thus allow a safer targeting of Cav-1 mediated radiation resistance." (PMID 28112237, 2017). "4, 6 Interestingly, knockdown of CAV1 in metastatic HCC cells had the opposite effect, suppressing tumour growth and metastatic potential in vivo." (PMID 29022911, 2017). "The epithelial cells that surround the periphery of the tumor were positive for CK 14 and in most areas also for CK19, Amelogenin, Glut-1, Epithelial Related Antigen (MOC-31) and Caveolin-1." (PMID 28390134, 2017). "Indeed, Cav-1 is emerging as a key component of circulating exosomes and is elevated, e.g., in melanoma and glioblastoma, while its expression in target cells plays a regulatory role in exosome internalization, essential for transmitting molecular information participating in tumor development." (PMID 28338624, 2017).
tumor (continued). "The epithelial cells that cover the periphery of the tumor showed immunopositivity for Cytokeratins 14 and 19, while Amelogenin, Glut-1, MOC-31, Caveolin-1." (PMID 28390134, 2017). "To this end, we assessed subcutaneous tumor growth of B16F10 cells expressing wild-type CAV1, CAV1(Y14F) or CAV1(Y14E)." (PMID 27259249, 2016). "BIRC3, CAV1, CAV2, FN1, ITGA1 and THBS1 were functionally enriched to focal adhesion, which contributes to antiangiogenic and anti-tumour effects." (PMID 27557147, 2016). "The fact that these five genes (MTHFD2, EIF4E, RMI1, CAV1 and HIF1A) are all very relevant in tumor biology further emphasizes a role of Wig-1 in the regulation of cell cycle and cell proliferation, as well as tumor onset, progression and metastasis." (PMID 26672765, 2016). "From a tumour targeting perspective, however, it was of interest that the strong hypoxic induction of CAIX internalization can override the negative regulation by caveolin-1." (PMID 27094744, 2016). "In the present study, we provide evidence demonstrating the critical functional role of Cav-1 in promoting LSS-induced invadopodia formation and tumor metastases." (PMID 26919102, 2016). "In summary, this study provides evidence that Cav-1 and its activation play critical roles in promoting LSS-induced invadopodia formation and tumor metastases." (PMID 26919102, 2016). "CAV1 and CAV2 were correlated with tumour growth and metastasis, and FN1 was a potential biomarker for some cancers, while ITGA1 and THBS1 were also associated with cancer risk." (PMID 27557147, 2016). "Indeed, CAV1 and caveolae, which mediate molecular trafficking and contain signaling molecules such as non-receptor tyrosine kinases and endothelial nitric oxide synthase (eNOS), have long been proposed as potential therapeutic targets for disrupting tumour angiogenesis, progression and metastasis." (PMID 27852311, 2016). "We first investigated if levels for caveolin 1, a protein involved with TBG nanocapsule entry by the caveolar or lipid-raft type mechanism in tumor cells, were differentially expressed." (PMID 27557516, 2016). "Our studies also demonstrate a novel role for Cav-1 in promoting JAK/STAT and JNK activation in tumor cells." (PMID 26065715, 2015). "Overall, our data establishes a novel interaction between Cav-1 and both JAK/STAT3 and JNK signaling in tumor cells, and we postulate that Cav-1 and caveolae directly promotes activation of STAT3 and JNK pathway activation through Src." (PMID 26065715, 2015). "Molecular analysis of NRAS and NRAS-ΔPTEN tumours was performed to evaluate the level of β-catenin, PTEN, CAV1 and the cell–cell adhesion molecule and β-catenin interactor, E-cadherin (ECAD)." (PMID 26307673, 2015). "High Cav1 expression in ECs protected experimental MPR31-4 tumors from microvascular damage, a critical component in the tumor response to radiotherapy." (PMID 25985209, 2015). "Thus, the effects of Cav-1 on aerobic glycolysis may be opposite in cancer cells and tumor stroma." (PMID 26431273, 2015). "Meanwhile, Cav-1 positively correlated with CSC self-renewal and the tumor biomarker CA19-9 in cancer patients." (PMID 26431273, 2015). "Downregulation of Cav1 induced EMT and enhanced tumor cell migration and invasion in various cancer cell lines." (PMID 26474461, 2015). "These vesicles were shown to contain bioactive matrix metalloproteinases (MMP2 and MMP9), enzymes that have critical importance in tumour invasion, in addition to RNA, ADP-ribosylation factor 6 and caveolin-1." (PMID 24931391, 2014). "Cav-1 and Cav-2 genes are located in a fragile site (known as D7S522 locus) that is frequently deleted in human cancers, indicating a common role as tumor suppressors." (PMID 24427291, 2014). "Here, we provide further evidence that Cav-1 is consistently phosphorylated through a Src-dependent mechanism in various ERMS and ARMS cell lines, playing a pivotal role in tumor growth and chemoresistance." (PMID 24427291, 2014).
tumor (continued). "To confirm the role of Cav-1 in the tumorigenicity of BSW cells, we assessed tumor growth and progression in vivo using a xenograft mouse model." (PMID 24939878, 2014). "Thirty one % (35/113) of tumours tested expressed all three markers and 19 % (21/112) had moderate or strong expression of ANXA1, CAV-1 and EphA2." (PMID 25594008, 2014). "In present study, we aimed to identify the expression status of CAV1 in HCC cell lines and tumor samples, in order to investigate the changes of CAV1 expression in HCC progression." (PMID 25180681, 2014). "We evaluated CAV1 expression levels in B16F10 (mock) and B16F10 (cav-1) cells before subcutaneous injection and after recovery from the primary tumours." (PMID 24500501, 2014). "These include caveolin 1 [which directly binds DLC1 and contributes to its tumor suppressive roles], CDKN1B [which is an inhibitor of and directly binds to CDK6], and cyclin D1 [which forms a complex with CDK6]." (PMID 25425654, 2014). "Considering the tumor promoting function of TGF-β in HCC, the cell lines were analyzed for TGF-β regulation of caveolin-1 expression." (PMID 23339737, 2013). "Thus, promoting tumor invasion and metastasis may not be the primary mechanisms by which loss of CAFs Cav-1 promotes GC development." (PMID 23527097, 2013). "Similar to Cav1, DLC1 is a tumor suppressor silenced or deleted in many human cancer entities including GC, e.g. by gene methylation." (PMID 23592983, 2013). "Because CAV1 has been shown to contribute to the progress of angiogenesis in different tumor entities, we sought to determine whether the impairment of tumor growth correlated with impaired angiogenesis as a consequence of CAV1 silencing and the mechanisms involved." (PMID 23951165, 2013). "We previously reported that caveolin-1 expression is significantly decreased in HBV-infected HCC tissues and closely correlates with tumor progression." (PMID 22894556, 2012). "CD133-positive cells, isolated from the tumor, expressed stem cell markers including nestin, CD133, Ki67, Sox2, EFNB1, EFNB2, EFNB3, Cav-1, Musashi, Nucleostemin, Notch 2, Notch 4, and Pax6." (PMID 22995409, 2012). "In particular, the EWS/FLI-1 protein expression is associated with activation of vascular endothelial growth factor (VEGF) and Caveolin-1 (CAV-1), which are known to contribute directly to tumor progression." (PMID 22523703, 2012). "MHCC-97 H cells are more invasive and malignant, and express less caveolin-1 than MHCC-97 L cells, which is consistent with its possible role as a tumor suppressor." (PMID 22894556, 2012). "Our results indicate the clinical importance of the stromal molecular expression of Cav-1 and LC3B and will potentially attract more attention to the exploration of the complicate tumor microenvironment." (PMID 23203033, 2012). "Importantly, they also observed an increased Cav-1 positivity in tumor-associated ECs, primarily restricted to regions with Cav-1-positive tumor cells, corresponding to the higher percentage of Cav-1-positive microvessels within these regions, as opposed to Cav-1-negative tumors." (PMID 26605130, 2012). "Regarding miR-133a in human cancers, our previous studies demonstrated that miR-133a functions as a tumor suppressor and targets multiple oncogenes, such as FSCN1, LASP1, CAV1 and GSTP1." (PMID 21378409, 2011). "Previously, we were able to show that CAV1 mRNA expression is higher in RCC compared to normal renal tissue and increases with tumour stage." (PMID 22152020, 2011). "Within the group there are regions coding for genes TES, CAV1 and CAV2, which perform tumor suppressor activities." (PMID 19919683, 2009). "Exosomes were purified from plasma of tumor patients (n = 90) and healthy donors (n = 58) and quantified by Exotest based on the expression of CD63 and Cav1." (PMID 19381331, 2009).
tumor (continued). "The analysis revealed that when caveolin-1 is coexpressed with either pAKT, pmTOR, pS6 or p4E-BP1 within the primary tumour, time to relapse was significantly reduced compared with when either of the individual variables were expressed alone." (PMID 18283322, 2008). "The downregulation of Cav-1 observed in cell lines derived from the HNSCC metastatic mouse model led us to examine Cav-1 expression in primary tumours and LNM of HNSCC tissue specimens by immunohistochemical analysis." (PMID 19002186, 2008). "Tumor growth inhibition with CDIM9 in vitro and in vivo correlated with increased p27 and caveolin-1 protein expression." (PMID 17764562, 2007). "Comparison of the BxPC-3 (derived from a primary tumor) and HPAF-II (derived from a metastasis) demonstrates a reciprocal relationship between cav-1 expression and p42/p44 Erk activation with PC cell migration, invasion, RhoC GTPase and p38 MAPK activation." (PMID 15969750, 2005). "In normal renal parenchyma (adjacent to some of the tumours), the strongest ICC staining for caveolin-1 was localised to proximal tubular epithelium cytoplasm in a fine granular pattern." (PMID 14612902, 2003). "FABP4 and vimentin expression was increased in proximity to the tumor, while caveolin-1, CD44, MMP9, and adiponectin showed minimal or no changes." (PMID 41596770, 2026). "Furthermore, we observed that CAV1 expression increases in patients progressing from NASH to NASH-HCC; however, high expression was also noted in non-tumour peripheral tissues." (PMID 40715090, 2025). "Given CAV1’s role in both tumour cells and stroma, therapeutic targeting of CAV1 in HCC may have dual benefits: inhibiting cancer cells while modulating the pro-carcinogenic microenvironment, potentially sensitising tumour cells to immunotherapy." (PMID 40715090, 2025). "The absence of Cav1 reduces hnRNPA1 levels in EVs, impairing their ability to promote tumor proliferation and migration." (PMID 40963741, 2025). "HCCs often overexpress CAV1, whose expression level may convert the response of HCCs to TGF-β from pro-apoptotic to tumor-promoting." (PMID 40260391, 2025). "For gedatolisib in combination with gefitinib, this additive effect was also verified by long-term colony-forming assays for HGSOC models expressing CAV1 and EGFR, as well as in long-term primary patient-derived organoid (PDO) cultures using early-passage tumor samples." (PMID 39482470, 2025). "Tumor-derived exosomes (TDEs) carry various bioactive molecules, including TGF-β, caveolin-1, HIF-1α, and β-catenin, which collectively enhance the invasive and migratory capabilities of recipient cells, promote immune evasion, and contribute to drug resistance." (PMID 40630801, 2025). "Moreover, exosomal miR-192/215 released under hypoxic conditions by HNSCC cells suppresses caveolin-1 (CAV1) expression in fibroblasts, thereby triggering TGF-β pathway activation and reprogramming the hypoxic tumor niche." (PMID 41583435, 2025). "However, notable protein-mRNA discordances emerged for CUBN, CAV1, DAB2IP, and GIPC1, which showed transcriptional upregulation in GSE208143 despite protein-level downregulation in most tumor subtypes." (PMID 41374987, 2025). "Further protein analysis via Western blotting revealed that the expression of CAV-1, ABCB1, and ABCC3 proteins in tumor tissues was significantly downregulated in the PPH + PTX group, with the degree of inhibition stronger than that observed in the lovastatin + PTX group." (PMID 41304944, 2025). "Surprisingly, a strong CAV1 versus EGFR mRNA correlation was observed in adjacent stromal cells for all disease stages, whereas, for tumor and adjacent epithelial cancer cells, the correlation was strong at the earlier disease stages only and diminished as stage progressed." (PMID 39482470, 2025). "Cav-1-positive EVs play a pivotal role in intercellular communication within the TME, facilitating the transfer of oncogenic signals, promoting drug resistance, and enhancing tumor aggressiveness." (PMID 40963741, 2025).